IL17A (interleukin 17A)
Diseases named in the same sentence as IL17A in open-access papers (continued):
Sharing a sentence is not in itself a finding about the gene and the disease.
plaque psoriasis (continued). "Recently, IL-17A blocking agents have been approved for the treatment of moderate-to-severe plaque psoriasis." (PMID 36289670, 2022). "Ixekizumab is a humanized IgG4 IL-17A monoclonal antibody, and secukinumab is a fully human IgG1 IL-17A monoclonal antibody, both highly effective in treating patients with moderate-to-severe plaque psoriasis in three phases of clinical trials." (PMID 36133421, 2022). "In our study, reduced m6A promoted inflammatory cell infiltration in the skin lesions and increased the expression levels of inflammatory cytokines closely related to psoriasis vulgaris, such as Il17a and Tnfα." (PMID 36293529, 2022). "Die mittelschwere bis schwere Psoriasis vulgaris kann wirksam mit immunmodulierenden Biologika wie dem Interleukin-17A-Inhibitor Secukinumab behandelt werden." (PMID 34417630, 2021). "The role of the IL-23/IL-17 pathway in the pathogenesis of plaque psoriasis is clearly validated by the clinical success of antibodies neutralizing IL-23p19, IL-17A or the IL-17A receptor." (PMID 34040108, 2021). "Moderate to severe plaque psoriasis can be treated effectively with immunomodulating biologicals such as the interleukin-17A inhibitor secukinumab." (PMID 34417630, 2021). "They found a broad activation of CD4+ T-cells with increased IL-17A and TNF production in blood and skin lesions of GPP patients, as well as increased infiltration of IL-17A+ cells in skin lesions from GPP as compared to plaque psoriasis patients." (PMID 33919434, 2021). "IL-17A and IL-17-regulated proinflammatory cytokines were highly expressed in Asian small plaque psoriasis, but lower in Western large plaque psoriasis." (PMID 35145980, 2021). "IL-17A is undetectable in normal skin; however, it was detected in skin lesions in allergic contact dermatitis and psoriasis vulgaris." (PMID 32587472, 2020). "Secukinumab is a human monoclonal IgG1 antibody that blocks IL-17A activity and was reported to be effective for plaque psoriasis." (PMID 31654299, 2020). "Plaque psoriasis also had more IL-17A and IFN-γ double producers than palmoplantar psoriasis (p = 0.044)." (PMID 30054515, 2018). "Conventional plaque psoriasis had a significantly higher percentage of IL-17A and TNF-α from CD8+ T cells relative to palmoplantar psoriasis (p = 0.044 and p = 0.044 respectively)." (PMID 30054515, 2018). "Ustekinumab (anti-IL-12/23) and secukinumab (anti-IL-17A) are both currently commercially available for the treatment of plaque psoriasis." (PMID 27347395, 2016). "Interleukin-17A inhibitors have been studied in large clinical trials in plaque psoriasis and ankylosing spondylitis." (PMID 27595932, 2016). "In combination with the results of other trials exploring antibodies directed against IL-17A 5 or the IL-17 receptor A chain 7, these studies document the potential of IL-17 blockade as a new therapeutic approach in moderate-to-severe plaque psoriasis." (PMID 25828362, 2015). "Given that IL-17 levels are increased in skin lesions and sera of psoriasis vulgaris patients, it is noteworthy that miR-1266 levels, a putative regulator of IL-17A, were also increased in the sera of these patients." (PMID 26236331, 2015). "The interleukin-17F and IL-17A contribute mainly to the pathobiology of plaque psoriasis and the simultaneous blockade of both cytokines may lead to more complete suppression of inflammation and superior clinical outcomes than blocking IL-17A alone." (PMID 39634792, 2024). "IL-17A and IL-17F are critical cytokines in the pathogenesis, especially in psoriasis vulgaris." (PMID 39519167, 2024). "Besides IL-17A and IL-23, two members of the IL-1 superfamily, IL-36α and IL-36γ, were found to be overexpressed in the epidermal compartment of psoriasis vulgaris skin lesions." (PMID 38162658, 2023).
plaque psoriasis (continued). "Psoriasis vulgaris or plaque psoriasis is the most prevalent subtype of this skin disease (about 90% of the cases), characterized by an overactive immune response, leading to a chronic expression of IL-23 and IL-17A cytokines." (PMID 38162658, 2023). "While this treatment is very effective in GPP, it remains an open question if an anti-IL36R antibody might also be beneficial for the treatment of IL-17A-dependent plaque psoriasis." (PMID 38162658, 2023). "In addition, the IL-17A antagonist (secukinumab) used to treat moderate to severe plaque psoriasis can significantly inhibit the secretion of CXCL1 and CXCL8 by keratinocytes, and almost completely eliminate the infiltration of neutrophils in skin lesions." (PMID 33613635, 2021). "Daily application of IMQ on mouse back skin induced inflamed scaly skin lesions resembling plaque psoriasis, characterized by increased epidermal proliferation, accumulation of immune cell infiltrate, neo-angiogenesis and high expression of IL-23, IL-17A and IL-36." (PMID 32352958, 2020). "In this study, the intravenous treatment of subjects with moderate-to-severe plaque psoriasis with the anti-IL-17A antibody secukinumab was used as a model to better understand disease mechanisms and to further dissect the response to IL-17A-targeting therapies." (PMID 25828362, 2015). "The role of the IL-23/IL-17 pathway as a key driver of skin inflammation is supported by the clinical efficacy of agents that block IL-23 or effector cytokines regulated by IL-23 (eg, IL-17A alone or in combination with IL-17F) in the treatment of plaque psoriasis." (PMID 39224116, 2024). "Thus inhibition of the IL-36 signaling pathway might potentially also inhibit IL-17A-driven inflammation in plaque psoriasis." (PMID 38162658, 2023). "It has been suggested that the IL-23 effects are dependent on IL-17A, which is also consistent with the findings that neutralizing anti-IL-17 antibodies, including Secukinumab and Ixekizumab, are approved as first-line treatment of moderate-to-severe plaque psoriasis." (PMID 34440590, 2021). "In conclusion, the existing evidence suggests that biologic therapies including TNFi, an anti‐IL‐12/23 agent (ustekiumab) and anti‐IL‐17A agents (secukinumab and ixekizumab) had no significant impact on the risk of MACEs in adult patients with plaque psoriasis over the short term." (PMID 27518205, 2017). "In this real-world prospective cohort study, IL-17A inhibitors (SEC and IXE) and the IL-23 inhibitor GUS demonstrated significant efficacy in improving both nail and skin lesions in patients with plaque psoriasis." (PMID 40264783, 2025). "Bimekizumab (BMK), a monoclonal antibody targeting IL-17, is a dual inhibitor of IL17 A and F that has shown efficacy in treating moderate to severe plaque psoriasis." (PMID 38541607, 2024). "There is currently a lack of real‐world clinical data regarding the safety and efficacy of coronavirus disease 2019 (COVID‐19) vaccines with respect to plaque psoriasis treatment involving tumor necrosis fact or (TNF)‐α and interleukin (IL‐17A) inhibitors." (PMID 37506146, 2023). "The expression of Th17/Th1-related cytokines, such as IL-17A, IL-22, IL-23p19, IFN-γ, and IL-18, is increased in plaque psoriasis when compared to GPP and normal skin." (PMID 34838431, 2022). "Ixekizumab is a humanized IgG4 monoclonal antibody that selectively binds to IL-17A, approved by the FDA and EMA for the treatment of adults and children six years and older with moderate to severe plaque psoriasis." (PMID 36232430, 2022). "In fact, secukinumab and ixekizumab, both IL-17A antibodies, have been FDA-approved for the treatment of plaque psoriasis based on phase 3 trials." (PMID 27595932, 2016).
plaque psoriasis (continued). "Antibodies targeting IL-17A have been approved for the treatment of plaque psoriasis; the observation in our cohort supports the rationale for combining anti-PD1 antibodies with IL-17A-targeted therapy in multiple cancer patients for overcoming immune suppression." (PMID 38349411, 2024). "There is currently a lack of real‐world clinical data regarding the safety and efficacy of coronavirus disease 2019 (COVID‐19) vaccines with respect to plaque psoriasis treatment involving tumor necrosis factor‐α (TNF‐α) and interleukin‐17A (IL‐17A) inhibitors." (PMID 37506146, 2023). "Whereas the importance of IL-17A to pathogenesis has now been convincingly demonstrated by successful treatment of patients with IL-17A antibodies, treatments targeting IL-1 receptor have shown efficacy only for pustular psoriasis, but not plaque psoriasis." (PMID 23915137, 2013). "Considering apremilast’s role in reducing IL-17F, IL-17A, IL-22, and TNF-α plasma levels in patients with moderate to severe plaque psoriasis, it could be hypothesized that apremilast acts as a pleiotropic molecule, blocking a common pathway shared by both PsO and MetS." (PMID 39204094, 2024). "Bimekizumab is a monoclonal IgG1 antibody that selectively inhibits IL‐17A and IL‐17F and was approved by National Institute for Health and Care Excellence in September 2021 for treating adults with moderate to severe plaque psoriasis after standard therapy was unsuccessful or not tolerated." (PMID 39355734, 2024). "Therefore, cytokines such as IL-17A, IL-22, IL-23, and TNF-α were found to be elevated in both psoriasis vulgaris and GPP; however, GPP lesions yielded significantly higher IL-1 and IL-36, and lower IL-17A and interferon-gamma (IFN-γ) messenger RNA (mRNA) expressions, than plaque psoriasis lesions." (PMID 34445754, 2021). "Investigation into Tc17 cell activation confirmed that CD8 + T cells are infiltrated in peripheral vascular walls and the subcutis in BD, and, concurrently, IL-17A + CD8 + T cells were elevated in BD compared to psoriasis vulgaris lesions and were a major source of IL-17A rather than CD4 + T cells." (PMID 34975900, 2021).
tuberculosis (187 papers, 2009 to 2026). A chronic, recurrent infection caused by the bacterium Mycobacterium tuberculosis. "and their metabolites are associated with the inhibited production of interferon‐γ and IL‐17A, which confer higher susceptibility to tuberculosis and other respiratory diseases, including severe COVID‐19 disease." (PMID 35578891, 2022). "IL17A has been found associated with the induction of autophagy in tuberculosis patients through a mechanism that activates MAPK1/3/14." (PMID 35153741, 2021). "Here, we show that the TCR/ITK signaling pathway is enriched in human lungs with active tuberculosis and that Itk deficiency impaired early protection against Mtb in mice, accompanied by defective development of IL-17A-producing γδ T cells in the lungs." (PMID 32038633, 2019). "Recently we have demonstrated that the Interleukin 17A (IL17A) rs2275913 SNP is associated with protection to tuberculosis but related to higher disease severity in Argentina." (PMID 29361774, 2018). "Overall, our findings demonstrated that the AA genotype from the IL-17A rs2275913 SNP is positively associated with protection to active tuberculosis but related to higher disease severity in the Argentinean population." (PMID 28098168, 2017). "Our previous work evidenced that higher levels of IL-17A were directly associated with tuberculosis severity." (PMID 28098168, 2017). "In order to investigate the association between IL-17A rs2275913 SNP and tuberculosis in Argentina, 185 TB and 207 HD were recruited between 2013 and 2016." (PMID 28098168, 2017). "Here, we investigated the association of the rs2275913 SNP (G → A) from IL-17A and tuberculosis in Argentina by a case-control study." (PMID 28098168, 2017). "Taken together, we describe for the first time, the existence of an association between the A allele form the rs2275913 SNP of the IL-17A and resistance to tuberculosis disease in Argentina." (PMID 28098168, 2017). "Overall, by comparing the HD and the TB populations, we found genetic evidences of an association between the IL-17A rs2275913 AA genotype and resistance to tuberculosis disease in Argentina, which was further supported by in vitro analyses." (PMID 28098168, 2017). "Single SNP analysis showed that rs3819024 in IL-17A and rs763780 in IL-17F were significantly associated with the treatment outcomes of tuberculosis." (PMID 27339100, 2016). "It is known that some polymorphisms in the genes encoding signature Th17-associated cytokines, IL-17A and IL-17A, may be associated with a predisposition to tuberculosis." (PMID 37626620, 2023). "Finally, whereas we recently showed a positive association of the IL17A rs2275913 SNP with protection against active tuberculosis, we also demonstrated that IL17A rs2275913 SNP is related to advanced disease in the Argentinean population." (PMID 31616423, 2019). "Therefore, the aim of this study was to investigate the potential association of the IL-17A rs2275913 SNP and tuberculosis in Argentina." (PMID 28098168, 2017). "Moreover, the fact of carrying a particular genotype that augments even more the synthesis of IL-17A would be harmful for tuberculosis outcome, given that we detected an association between AA genotype with clinical and immunological parameters of disease severity." (PMID 28098168, 2017). "The study also explored SNPs in IL-17A (rs3819024) and IL-17F (rs763780), which were found to have a relationship with tuberculosis prognosis." (PMID 39459627, 2024). "tuberculosis coinfections in Indian adults are associated with lower circulating levels of inflammatory cytokines, including IFN-γ, TNF-α, IL-17A, and IL-17F alongside increased type 2 cytokines IL-4, IL-5, and IL-13." (PMID 39816832, 2023). "During experimental tuberculosis (TB), interleukin (IL)-17A appears to be involved in the formation of lung granulomas, possibly through the attraction of neutrophils to the sites of infection." (PMID 36139450, 2022).
tuberculosis (continued). "Nodal analysis revealed that IL-17A again had the greatest nodal connectivity in ART-naive participants with HIV–tuberculosis co-infection, with IL-1β and TNFα in second and third place." (PMID 34386782, 2021). "Interleukin (IL)-17A emerged as a key correlate of HIV-1-induced inflammation during HIV–tuberculosis co-infection." (PMID 34386782, 2021). "Whereas, the contribution of IL17A in immunity to tuberculosis is usually accepted, the role of IL17F has been scarcely studied so far." (PMID 31616423, 2019). "During primary tuberculosis, IL-17-producing cells are induced, leading to IL-17A synthesis, which is a potent inflammatory cytokine capable of increase chemokines expression that promotes cell recruitment and granuloma organization." (PMID 28871251, 2017). "Although preclinical studies have demonstrated that IL-17A induces neutrophil recruitment and a local inflammatory response via cytokine and chemokine secretion from tissue-resident cells, the functions of IL-23 and IL-17 in tuberculosis appear to be more subtle than those of Th1 cytokines." (PMID 38137722, 2023). "These mechanistic studies might reveal whether IL-17A-related inflammatory pathways are a cause or consequence of detrimental outcomes in HIV-1 and HIV–tuberculosis co-infection and thus potentially inform novel therapeutic targets." (PMID 34386782, 2021). "IL-17A network connectivity thus serves as a read-out of higher systemic inflammation and immune activation induced by advanced HIV-1 infection and uncontrolled HIV-1 viral replication, and denotes increased mortality risk in HIV–tuberculosis co-infection." (PMID 34386782, 2021). "Further mechanistic studies are required to identify specific IL-17A-related inflammatory pathways mediating immunopathology in HIV–tuberculosis co-infection, which could illuminate targets for future host-directed therapies." (PMID 34386782, 2021). "The number of connections with IL-17A through network analysis had 88% sensitivity and 89% specificity to differentiate those who died versus those who survived hospital admission for HIV-1-associated tuberculosis." (PMID 34386782, 2021). "In addition, IFNG and IL22 gene expression is also increased in tuberculosis LN, but the expression of IL17A was unaffected." (PMID 33057074, 2020). "We show here that human lungs with active tuberculosis exhibit altered T-cell receptor/ITK signaling and that Itk deficiency impaired early protection against Mtb in mice, accompanied by defective development of IL-17A-producing γδ T cells in the lungs." (PMID 32038633, 2019). "The immunopathological potential of IL-17A during autoimmune and infectious episodes suggests that IL-17A may have a detrimental effect in chronic bacterial infections such as tuberculosis (TB), particularly during late stages of disease." (PMID 31736982, 2019). "However, in TB the production of IL-17A would be higher as compared to HD, since tuberculosis exacerbates its secretion." (PMID 28098168, 2017). "Thus, our data are consistent with previous reports, further supporting the idea of a higher resistance to tuberculosis disease in AA individuals and highlighting the important function of IL-17A in immunity against Mtb." (PMID 28098168, 2017). "The identification of the rs2275913 AA genotype as a biomarker of tuberculosis protection and the role of the IL-17A in the immune-physiology of tuberculosis might contribute to design more effective vaccines and to identify risky sub-populations in Argentina." (PMID 28098168, 2017). "Moreover, we found that SNPs of rs3819024 in IL-17A and rs763780 in IL-17F were weakly related to a prognosis of tuberculosis." (PMID 27339100, 2016). "Thus, our observations also support the notion that IL-17A is involved both in immune processes leading to protection or immunopathology of tuberculosis." (PMID 22359547, 2012).